SNAP25 (synaptosome associated protein 25)
Diseases named in the same sentence as SNAP25 in open-access papers (continued):
Sharing a sentence is not in itself a finding about the gene and the disease.
diabetes (14 papers, 2009 to 2024). "Meanwhile, significant associations are detected between SNAP25 polymprphism rs363050 and increasing fasting glucose, HbA1c, and lower insulin in type 2 diabetes mellitus (T2DM) patients." (PMID 38371897, 2023). "The role that down-regulation of synaptosomal-associated protein 25 (Snap25) found between the Akita.PlGF−/− versus the Akita groups play in diabetes is suggested from literature." (PMID 30425286, 2018). "A possible role of Snap25 polymorphisms in type 2 diabetes mellitus (T2DM) was evaluated by analyzing three SNPs within intron 1 in a region known to affect the gene expression in vitro." (PMID 26779543, 2016). "Caffeine consumption attenuated the diabetes-induced decrease of SNAP25 and synaptophysin immunoreactivity, whereas it was devoid of effects in control mice." (PMID 22514596, 2012). "Interestingly, we found that caffeine prevented the diabetes-induced loss of SNAP25 but not of synaptophysin." (PMID 30686981, 2018). "Quantitation of the protein expression of α2-AR/SNAP-25 showed a significant elevation, whereas the α2-AR/PSD-95 remained unaltered as a function of diabetes." (PMID 36297581, 2022). "The presynaptic proteins synaptophysin, synapsin 1, VAMP2, SNAP25, and PSD95 all show decreases after only one month of diabetes, especially when synaptosomal fractions are selectively examined." (PMID 19936028, 2009).
autism (13 papers, 2015 to 2024). Persistent deficits in social interaction and communication and interaction as well as a markedly restricted repertoire of activity and interest as well as repetitive patterns of behavior. "Beyond its role in the presynaptic initiation of neuronal signalling and association with autism-relevant behaviours, SNAP-25 influences dendritic spine formation via binding to the postsynaptic protein, p140Cap57." (PMID 32879325, 2020). "Therefore, the STRING analysis revealed a robust interaction between the STXBP6 and SNAP25 genes, reinforcing the well-documented association of SNAP25 with autism." (PMID 38003627, 2023). "This study is the first to identify an increased density of DG hippocampal microglia and decreased expression of cortical SNAP-25 in the NL3R451C mouse model of autism." (PMID 32879325, 2020). "Here, we report differential changes in the level of SNAP-25 protein and in the expression of Snap25 gene in the brain of juvenile male rats in two chemical models of autism induced by exposure in the critical period of fetal life to teratogens VPA and THAL." (PMID 32367505, 2020). "Furthermore, genetic variants of SNAP25 leading to low protein expression levels have been associated with hyperactivity and/or with low cognitive scores in autistic patients, corroborating our results linking differentially expressed proteins in Fgf14−/− mice with autism." (PMID 30678040, 2019). "Likewise, many neuronal genes with H3K27ac gain and increased expression under CHD2 deficient conditions are linked to the etiology of autism and other NDDs, including MYT1L, NRXN3, SLC12A5, and SNAP25 32–35." (PMID 36115870, 2022). "This is the first use of rat chemical models of autism to verify the hypothesis that disturbances in SNAP-25 protein expression may be involved in the pathophysiology of ASD." (PMID 32367505, 2020). "Although protein–protein interaction data are far from complete, this suggests that Snap25 and Aldh1a1 may be key players in the pathogenesis observed in Fgf14−/− mice and perhaps SZ and/or autism." (PMID 30678040, 2019). "This interaction appears to mediate subsequent interactions with a network of other autism-related genes’ protein, including CYFIP1, MAPT, APBB1, SNAP25, and CDK16." (PMID 39376742, 2024). "Thus, the aim of this project was to investigate whether the fetal exposure of rats to VPA or THAL, which are known to induce behavioral deficits similar to ASD and represent the two established animal models of autism, can also modify the expression of SNAP-25 in the brain of juvenile animals." (PMID 32367505, 2020). "However, this hypothesis could not be verified based on the literature because, to our knowledge, there have been no complex studies examining SNAP-25 expression using VPA and THAL rat models of autism." (PMID 32367505, 2020).
epilepsy (13 papers, 2011 to 2026). A brain disorder characterized by episodes of abnormally increased neuronal discharge resulting in transient episodes of sensory or motor neurological dysfunction, or psychic dysfunction. "This is supported by the presence of the nonsense variants c.520C > T (p.Gln174*) and c.589C > T (p.Gln197*) in SNAP25, associated with epilepsy and speech difficulties." (PMID 38245625, 2024). "Deficits in the subunits of the core complex (synaptobrevin-2, syntaxin-1B and SNAP-25), Munc18-1 and complexin-1 are mainly associated with an overlapping spectrum of developmental delay, intellectual disability, epilepsy, and movement disorders." (PMID 35095745, 2021). "Genes most frequently shared among class 1 modules (such as DLG4, GRIN2A, PRKCB, and SNAP25) have been associated with epilepsy, synaptic function, and neuronal processes." (PMID 31653223, 2019). "Mutations in the plasma membrane SNARE protein SNAP-25 result in epilepsy and intellectual disability; these mutations occur in or near residues that bind directly to the C2B domain of SYT1." (PMID 30107533, 2018). "However, the possibility that causes other than epilepsy may induce the iDG phenotype in SNAP-25 KI mice cannot be excluded." (PMID 23497716, 2013). "In SNAP-25 KI mice, epilepsy is observed after postnatal day 21–25, and, as observed in the current study, treatment with the antiepileptic drug valproate rescued the iDG phenotype, enlargement of the DG, and working memory deficit." (PMID 23497716, 2013). "Recently, increases in anxiety-related behaviors and epilepsy have been observed in SNAP-25 knock-in (KI) mice, which have a single amino acid substitution of Ala for Ser187." (PMID 23497716, 2013). "To overcome this point, we also explored the therapeutic potential of BoNT/A in epilepsy, since a single BoNT/A injection into the mouse hippocampus resulted in a longer-lasting blockade of glutamate release due to the production of a shorter SNAP-25 fragment." (PMID 37755976, 2023). "Taken together, this study suggests that the iDG phenotype in SNAP-25 KI mice may be induced by epilepsy and may result in behavioral deficits." (PMID 23497716, 2013). "It has been suggested that changes in SNAP25 gene expression may also contribute to epilepsy." (PMID 25571999, 2015). "Immunoblotting analysis using phosphorylation-specific antibodies revealed that the phosphorylation of SNAP-25 at Ser187 also occurred in brain and interestingly the phosphorylation of SNAP-25 was dramatically changed in epilepsy." (PMID 21949876, 2011). "SNAP-25 stimulates γ-aminobutyric acid (GABA) release during development and it is expressed in the synaptic anterior of mature GABA neurons, involved in neurotransmission, and closely related with epilepsy." (PMID 23028951, 2012). "Thus, it is likely that the iDG phenotype is non-cell autonomously induced via epilepsy in SNAP-25 KI mice." (PMID 23497716, 2013). "However, the possibility that valproate rescues the phenotype in SNAP-25 KI mice in a manner independent of epilepsy cannot be excluded at this time." (PMID 23497716, 2013).
bipolar disorder (11 papers, 2013 to 2024). A disorder of the brain that causes unusual shifts in mood, energy, activity levels and the ability to carry out day-to-day tasks. "The rs3746544 and rs1051312 SNPs in the 3′ UTR region of the SNAP-25 gene have been thoroughly investigated as possible risk factors of ADHD or bipolar disorder, however the molecular function of these variants has not yet been studied." (PMID 24391914, 2013).
Anxiety (8 papers, 2013 to 2025). Intense feelings of nervousness, tension, or panic often arise in response to interpersonal stresses. "Studies using the mouse model with single amino acid mutations in Snap25 showed the induction of strong anxiety-related behavior." (PMID 32367505, 2020). "The haploinsufficiency caused by heterozygous deletion of SNAP25 in SNAP25(+/−) mice results in decreased ambulation in open field test without any other abnormalities in behavioral tests assessing anxiety-like behavior, learning, and memory or prepulse inhibition." (PMID 37066095, 2023). "We also identified differentially expressed genes involved in anxiety, mood, emotion (Cartpt, Snap25, Rxfp1, Nr1d1, Sept5), and neuropsychiatric disorders (YWHA-family)." (PMID 40978196, 2025). "We have also detected increased immunoreactivity for cleaved SNAP-25 in BLAm that play a role in anxiety-induced learning processes and exhibit hyperexcitability in anxiety and panic disorders." (PMID 36675200, 2023). "Using a dominant-negative SNAP-25 mutant (SNAP-25 knock-in [KI] mice), in which Ser187 is replaced with Ala, we have previously shown that this mutation results in an increase in anxiety-like behaviors and epileptic seizures." (PMID 23497716, 2013).
Parkinson disease (8 papers, 2017 to 2025). A progressive degenerative disorder of the central nervous system characterized by loss of dopamine producing neurons in the substantia nigra and the presence of Lewy bodies in the substantia nigra and locus coeruleus. "Concentrations SNAP25 and neurogranin were increased in cerebrospinal fluid of Parkinson’s disease patients in a disease specific manner and related to cognitive and motor symptom severity." (PMID 28649607, 2017). "An overall increase in the concentration of SNAP25 was found in Parkinson’s disease patients (p = 0.032)." (PMID 28649607, 2017). "Interestingly, elevated SNAP-25 levels are also observed in Parkinson’s disease (PD) and Creutzfeldt–Jakob disease (CJD), highlighting its potential relevance across a variety of neurodegenerative conditions." (PMID 40864734, 2025). "It is noteworthy that SNAP25 is also found to be altered in other neurological diseases, such as vascular dementia and Parkinson’s disease, indicating that synaptic protein supplementation strategy may be generalized beyond AD." (PMID 38528511, 2024).
type 2 diabetes mellitus (8 papers, 2016 to 2025). A type of diabetes mellitus that is characterized by insulin resistance or desensitization and increased blood glucose levels. "For SNAP25, high expression was significantly associated with basal cell carcinoma, primary immunodeficiency, and maturity-onset diabetes of the young." (PMID 41009659, 2025). "In human studies, SNAP25 gene single nucleotide polymorphism (SNP, rs362551) associated with severity of metabolic syndrome and type 2 diabetes." (PMID 34526970, 2021).
depression (7 papers, 2014 to 2025). "SNAP-25 is already implicated in short-term depression at the NMJ and it will be interesting to see if an additional role for SNAP-25 modulation in neuromuscular long-term depression will emerge, as recently observed in the hippocampus." (PMID 24489862, 2014). "In the hippocampus, in addition to a decrease in the level of SNAP-25 in the model of depression and the coexistence of depression and hypothyroidism, there was also a decrease in the level of the receptor for glucagon-like peptide 2 (GLP-2R) in all three tested models." (PMID 35951260, 2022). "PF significantly alleviated LPS-induced depression-like behaviors, increased hippocampal neuron and dendritic spine density, and upregulated synaptic proteins (PSD95, SNAP25, and BDNF)." (PMID 40427467, 2025). "Dysregulated neurogenesis and synaptogenesis have been reported in the brain of patients with major depressive disorders and multiple molecular pathways are believed to be disrupted in these processes, including BDNF, TrkB, PSD95, and SNAP25." (PMID 33526073, 2021). "NH125 treatment reduced the phosphorylation levels of eEF2 and mTOR, while enhanced BDNF and eventually SNAP25 and PSD95 expression, suggesting an etiological role of eEF2 in LPS-induced synaptogenetic dysfunction and depression." (PMID 33526073, 2021). "A significant positive correlation was observed between s129 volume and SNAP25 within DAT terminals in DLB cases with depression (rs = 0.379, p = 0.007), but not in DLB cases without depression or controls." (PMID 40113786, 2025). "Mice treated with LPS displayed depression-like behaviors, pronounced neuroinflammation, increased HDAC1 expression, and reduced eEF2 activity, as accompanied by altered synaptogenic factors including BDNF, SNAP25, and PSD95." (PMID 33526073, 2021). "A significant positive correlation between the volume of s129 and SNAP25 within presynaptic 5HTT terminals was observed in DLB overall (rs = 0.288, p = 0.012), non-depressed DLB (rs = 0.313, p = 0.016) and DLB with depression (rs = 0.316, p = 0.030)." (PMID 40113786, 2025).
glioma (7 papers, 2020 to 2025). A benign or malignant brain and spinal cord tumor that arises from glial cells (astrocytes, oligodendrocytes, ependymal cells). "Synaptosomal-associated protein 25 (SNAP25), a synaptic plasticity protein, is significantly correlated with the progression of glioma." (PMID 41018101, 2025). "Taken together, these results suggest that SNAP25 downregulation is associated with poor clinical outcomes of glioma." (PMID 34490096, 2021). "The effect of SNAP25 on glioma progression was studied, and the underlying metabolic and synaptic plasticity by which SNAP25 regulated glioma cell phenotype was also investigated." (PMID 34490096, 2021). "Overexpressed synaptosomal-associated protein 25 (SNAP25) has been demonstrated to regulate GLS-mediated glutaminolysis, thereby inhibiting glioma cell growth in vitro and in vivo." (PMID 38918694, 2024). "A recent study reported that SNAP25 inhibited glioma cell proliferation, migration and invasion by regulating the metabolism of glutamate." (PMID 38115820, 2023). "Since SNAP25 has been shown to play a vital role in glioma progression and glutamate metabolism, we next investigated the way SNAP25 functioned in this process." (PMID 34490096, 2021). "Violin plot showed the exact changing level of these genes as SNAP25 expression in glioma was significantly lower than that in normal brain tissue (p=0.001)." (PMID 34490096, 2021). "The wound-healing assay indicated that the motility of gliomas cells with stable SNAP25 silencing was significantly increased, while in SNAP25-upregulated cells was decreased (p<0.05)." (PMID 34490096, 2021). "The data above revealed that SNAP25 acted as an tumor suppressor in glioma and inhibited the progression of glioma." (PMID 34490096, 2021). "Conversely, SNAP25 knockdown accelerated cell proliferation, migration and invasion, and decreased glutaminolysis of glioma cells." (PMID 34490096, 2021). "Taken together, these studies elucidate a fundamental dimension of the glioma microenvironment and identify a robust and targetable mechanism of SNAP25 driving glioma proliferation and progression." (PMID 34490096, 2021). "We found that SNAP25 was downexpressed in the glioma tissues and cells, and lower expression of SNAP25 showed an unfavorable prognosis in glioma patients." (PMID 34490096, 2021). "The synaptic signature SNAP25 identified in our study exhibited potential as a biomarker of OS in glioma patients and indicated a relationship between neuron-glioma cell interaction and glioma progression." (PMID 34490096, 2021). "We confirmed that GLS acted as a metabolic target of SNAP25 and consequently decelerated glioma progression." (PMID 34490096, 2021). "In this study, the metabolic activity of glioma cells showed a significant discrepancy between SNAP25 overexpression and SNAP25 control cell groups and glutathione metabolism, alanine, aspartate and glutamate metabolism largely contributed to their separation." (PMID 34490096, 2021). "Transwell assays were implemented to evaluate the migration ability of glioma cells, and reduced migration ability of U118 and A172 cells with stable SNAP25 overexpression was observed (p<0.05)." (PMID 34490096, 2021). "Negative correlation between GLS expression and WHO grading was observed by immunohistochemistry assay, reflecting the similar expression pattern of GLS and SNAP25 in glioma." (PMID 34490096, 2021). "RT-qPCR, western blot, and immunohistochemistry assays were performed to examine the expression level of SNAP25 in glioma cells and samples." (PMID 34490096, 2021). "SNAP25 inhibited cell proliferation, migration, invasion and fostered glutamine metabolism of glioma cells, exerting a tumor suppressor role." (PMID 34490096, 2021). "SNAP25 was decreased in level of expression in glioma tissues and cell lines, and low-level SNAP25 indicated an unfavorable prognosis of glioma patients." (PMID 34490096, 2021).